RNU6-445P (RNA, U6 small nuclear 445, pseudogene)
Gene: Small nuclear RNA gene on chromosome 9 (74,857,675 to 74,857,781, forward strand). Ensembl gene ENSG00000252758.
Homologues: Orthologues: chimpanzee U6 (97% identical), macaque U6 (96% identical). Paralogues in human: RNU6-1331P (89% identical), RNU6-15P (88% identical), RNU6-1091P (87% identical), RNU6-166P (87% identical), RNU6-25P (87% identical), RNU6-41P (87% identical), RNU6-74P (87% identical), RNU6-797P (87% identical), RNU6-944P (87% identical), RNU6-1 (86% identical), RNU6-1060P (86% identical), RNU6-1145P (86% identical), and 1288 more.